FOXO3 (forkhead box O3)
Diseases named in the same sentence as FOXO3 in open-access papers (continued):
Sharing a sentence is not in itself a finding about the gene and the disease.
cancer (continued). "Before investigating whether, as observed in cancer cells, TFP impacts AKT/FOXO3 signaling, we first determined whether increased AKT/FOXO3 signaling is a feature of the hyperproliferative and apoptosis-resistant PAH-PASMCs." (PMID 33805714, 2021). "The importance of AKT-dependent cytosolic localization of FOXO3 in the cancer-like phenotype of PAH-PASMCs was further highlighted by forced expression of a FOXO3 mutant lacking the AKT phosphorylation sites." (PMID 33805714, 2021). "Although the potential therapeutic consequences and functions are yet to be determined, multiple genes associated with cancer or implied in non-hematologic malignancies were found as fusion partner genes in our dataset (e.g. CHD4, HOXA7, FOXO3)." (PMID 34340673, 2021). "The connection between FOXO3 and pyroptosis was reported previously, but there has been no report integrating Met, FOXO3, pyroptosis, and cancer." (PMID 34546972, 2021). "•GCN2 and PERK regulate FOXO3 via JNK and AKT in response to cancer drug." (PMID 32615282, 2020). "The Forkhead box O3 (FOXO3) transcription factor plays a pivotal role in promoting cell cycle arrest, senescence and cell death, as well as mediating the cytotoxic functions of cancer therapeutics." (PMID 32615282, 2020). "Furthermore, miR-132, miR-223 and miR-27a can induce proliferative arrest and cancer cell death through FOXO1 and FOXO3." (PMID 32372224, 2020). "Therefore, in addition, our data also suggest that the regulation of FOXO3 by PERK is predominantly mediated through the phosphorylation (T32) and inactivation by AKT in the drug-sensitive cancer cells." (PMID 31312024, 2019). "Our work also identifies the adaptive response of low FOXO3 expression to boost drug survival and the overdependence on elevated PERK activity to overcome heightened ER-stress, as an acquired vulnerability of the drug-resistant cancer cells." (PMID 31312024, 2019). "In addition, FOXO proteins (FOXO1, FOXO3 and FOXO4) are putative targets for prevention cancer therapy-related drug resistance." (PMID 31450545, 2019). "Together with FOXO3 activation, FOXO1 overexpression via miRNA interactions is involved in upregulation of ABCB1 gene, coding for P-glycoprotein, well known responsible for decreased drug accumulation in multidrug-resistant cancer cells." (PMID 31234353, 2019). "These three genes (i.e. FOXO3, NCOA3, and TCF7L2) also play roles in other human cancers." (PMID 29301589, 2018). "Similarly, the anti-cancer small molecule ONC201/TIC10 has also been shown to inhibit colorectal CSC self-renewal via inhibiting Akt and ERK, and consequently activating FOXO3 to induce the expression of the death receptors TRAIL and DR5 (TRAIL-RII)." (PMID 29180117, 2018). "FOXOs, comprising FOXO1, FOXO3, FOXO4, and FOXO6, are the focus of cancer research recently." (PMID 30046342, 2018). "As earlier reported, circ-Foxo3 expression was downregulated in several cancer cells than in non-cancer cells, and overexpressed circ-Foxo3 inhibited cell proliferation through binding to CDK2 and p21." (PMID 28219405, 2017). "Importantly, we show that AMPK activation and AMPK-dependent FoxO3 phosphorylation are upregulated in cachectic cancer patients, hinting for a conserved role of AMPK/FoxO3 interplay in cancer cachexia." (PMID 29167426, 2017). "Indeed, REP1 plays an important role in cancer progression, which is regulated by intracellular localization of EGFR or FOXO3." (PMID 28846638, 2017). "In proliferating cancer cells, survival signals trigger PI3K to activate Akt which in turn phosphorylates and inhibits specific pro-apoptotic targets such as Bad, caspase-9, and FOXO3." (PMID 27283899, 2016).
cancer (continued). "This study presents the opposite result to the previous study about the anti-cancer effect of casticin and has significance in that the activation of AMPK/FOXO3 signaling can show anti-cancer effects, such as autophagy and apoptosis with a different phosphorylation status of FOXO3." (PMID 39334758, 2024). "However, in cancer cells, the activity of FOXO1 and FOXO3 is often dysregulated." (PMID 38994962, 2024). "Similarly, for INMON, FOXO3 and IRF5 were common TFs in healthy and early-stage tissues (e.g., BRCA1-mut); specifically, PRDM4 was the TF in precancer stages (e.g., Goiters and HT) while ATF2 and RUNX1 were enriched in cancers (e.g., ESCC and IDC)." (PMID 38645221, 2024). "The exact mechanisms by which FOXO3 regulates aging and cancer in humans are not fully understood." (PMID 39334758, 2024). "In carcinoma, OA could increase ROS level, induce apoptosis, suppress angiogenesis and enhance mitochondrial dysfunction via inactivating sirtuin 1 (SIRT1)-forkhead box O3 (FOXO3)-BNIP3 axis." (PMID 36081929, 2022). "Furthermore, we found that expression of multiple key autophagy-related genes is positively correlated with FOXO3 in HCC patients, suggesting that elevated FOXO3 levels could be related to possible protective autophagy induction in this cancer type." (PMID 34769197, 2021). "As we predicted that FOXO3 was a target of miR‐23a‐3p and LINC00472 could bind to miR‐23a‐3p based on the bioinformatic analysis, we speculated the functionality of LINC00472 as a ceRNA of miR‐23a‐3p to regulate FOXO3 and subsequently influence BID‐dependent cancer cell apoptosis." (PMID 34363438, 2021). "The proposed mechanism of the miR-1247-5p–FOXO3 axis may be helpful for better understanding the role of LINC01124 in HCC oncogenesis and promoting the identification of promising therapeutic strategies for cancer treatment." (PMID 37304672, 2021). "Furthermore, predicted activation of FOXO3 and inhibition of FOXM1 provides a positive FOXO3/FOXM1 ratio which is considered to be favorable, since these factors are crucial in various aspects of cancer progression." (PMID 30717152, 2019). "Therefore, targeting FOXO3, FOXM1 and other upstream or downstream targets in the signalling pathways, could be a feasible strategy for cancer treatment and for overwhelming drug resistance." (PMID 29180117, 2018). "This review will focus on the role and regulation of FOXO3 and its key downstream target FOXM1, and discuss their central roles as modulators of fundamental cellular processes with special emphasis on our understanding of the current therapeutic potential of targeting the FOXO3-FOXM1 axis in cancer." (PMID 29180117, 2018). "Our data, showing that CDK6 phosphorylates and thereby stabilizes FOXO3, are highly reminiscent of the effects elicited on FOXM1, a related transcription factor, that, following phosphorylation by CDK4 and CDK6, is stabilized and transactivated to prevent senescence of cancer cells." (PMID 28778953, 2017). "We also confirmed that these anti-cancer agents did not suppress the FOXO3/CD44 axis." (PMID 28507327, 2017). "In addition, members of the FOXO family, such as FOXO1, FOXO3, FOXO4, and FOXO6, have been found to participate in various physiological responses, such as DNA damage, caloric restriction and oxidative stress, and play crucial roles in cancer initiation, progression, and chemo‐resistance." (PMID 32368828, 2020). "However, the fact that FOXO3 is often inactivated in cancer cells and even more so in the drug resistant cells, suggesting that the ability of FOXO3 to induce PERK in response to GCN2 inactivation is compromised in the cancer cells, and even more in the drug resistant cells." (PMID 32615282, 2020).
cancer (continued). "Specifically, circ-Foxo3 could interact with senescence-related proteins ID1 and E2F1, and stress elated proteins HIF1a and FAK, facilitating the locations of these transcriptional factors in the cytoplasm and accordingly increased stress-induced senescence and apoptosis in human cancer cells." (PMID 32061256, 2020). "Of the genes expressed, cancer exosomes consistently contained GALNT1 and LASS2 transcripts while lacking FOXO3 and ARHGEF39 expression, with the opposite being true for the healthy samples." (PMID 33803085, 2021). "Even though our study proved the potential of FOXO3 as a negative prognostic factor in HCC, additional large-scale investigations should be performed in this cancer type to confirm such an encouraging result." (PMID 34771514, 2021). "Currently, there is no literature to our knowledge that demonstrates FOXO3 is required for the caspase-3-mediated cleavage of PARP1 and caspase-3 proteins and for auranofin-induced apoptotic signaling in cancer cells." (PMID 25096914, 2014). "LASS2 and GALNT1 were only present in samples from cancer group, meanwhile ARHGEF39 (in the array named Chromosome 9 open reading frame 100 (C9orf100)) and FOXO3 were absent in cancer group and could be detected in control group." (PMID 24458310, 2014). "Although we did not observe any significant difference of FOXO3 mRNA expression between livers from HCC patients and non-HCC patients (n = 11, P = 0.10), we observed FOXO3-positivity in HCC patients mainly in cancer cells but not in stroma, where FOXO3 was localized in the nucleus." (PMID 31488102, 2019).
infection (49 papers, 2010 to 2026). The state of being infected such as from the introduction of a foreign agent such as serum, vaccine, antigenic substance or organism. "Next, FoxO1 and FoxO3 deficient cells were infected at high and low MOIs, and virus replication was monitored through the time course of infection." (PMID 36016282, 2022). "Infection caused due to bacteria blocked FoxO3 and over-stimulated cytokine production in the epithelial cells of intestine, whereas TNF-α-induced FoxO3 inactivation boosted IL-8 in HT-29 cells." (PMID 35156517, 2022). "Furthermore, infection of T cell-specific conditional FOXO3-deficient mice with LCMV, fully recapitulated the enhanced CD8 T cell expansion seen in global FOXO3−/− mice; even in the absence of CD4 T cells." (PMID 22359505, 2012). "Infection with melusin‐expressing adeno‐associated virus ameliorated contractile properties of 7 day unloaded muscles (P ≤ 0.05) and relieved myofiber atrophy (−33%) by reducing Atrogin‐1 and MurF‐1 transcripts (P ≤ 0.002), despite of a two‐fold increase in FoxO3 protein levels (P = 0.03)." (PMID 32154658, 2020). "The co-immunoprecipitation (Co-IP) assay further verified the interaction between FOXO3 and HDAC2 in wild type (WT) macrophages, while this association was weakened upon Pg inoculation, but restored under KDP136 infection." (PMID 40404630, 2025). "Among the FOXOs, FOXO3 modulates innate immune responses to infections of the airway epithelium through modulation of secretion of several cytokines from immune cells." (PMID 38816514, 2024). "In a separate set of experiments with a focus on FoxO3, we first verified FoxO3 OE following Ad-FoxO3 infection." (PMID 37693008, 2023). "Following infection in Kashmir favorella, three differentially expressed genes Nuclear Factor Kappa B (NF-κB1), Forkhead Box Protein O3 (FOXO3) and Paired box 5 (Pax5) were identified." (PMID 37098463, 2023). "Our data show that the Ca2+-AMPK pathway is required for transcriptional activation of the essential autophagy genes Gabarap, Gabarapl1, Map1lc3a, and Foxo3 in the context of myeloid-specific Gabra4 signaling during infection." (PMID 40395295, 2023). "The transcriptome analysis showed an increase in FoxO1 and FoxO3 mRNAs early in infection (4 h.p.i.), however, the results were somewhat inconclusive for the FoxO4 transcript due to the low number of the reads (not shown)." (PMID 36016282, 2022). "FoxO3 plays an extremely important role in overseeing innate immune responses to infections in the airway epithelium." (PMID 36233176, 2022). "FoxO3 plays an extremely important role in overseeing innate immune responses to infections faced by the airway epithelium." (PMID 34102081, 2021). "We have previously shown that FOXO3 activation, through inhibition of Akt signaling, at the primary site of infection dampens IL-10 release, increases antigenic presentation of APCs and results in intracellular clearance of BCG." (PMID 34122406, 2021). "FoxO3 overexpression adenovirus (Ad-FoxO3) infection induced increased lipid droplets in HepG2 cells, as shown by Oil red O staining." (PMID 31729980, 2019). "Forkhead box O3a (Foxo3a) not only directly phosphorylates IκB but also functions in the activation of NF-κB pathway in the infection disease." (PMID 29100348, 2017). "In keeping with this notion, infection of the keratinocytes with FOXO3 shRNA lentivirus resulted in a significant decrease in the basal rate of 3H -thymidine incorporation." (PMID 25647160, 2015). "Like FoxO1, FoxO3 regulates T and B lymphocyte survival and cell cycle progression, but FoxO3 additionally controls survival and entry of memory T cells into a quiescent state, critical for later response to infection." (PMID 24757526, 2014). "FoxO3 also has similar roles in B cells, and is likely important for terminating immune responses to infection, and possibly for controlling lymphocyte responses that would result in autoimmunity." (PMID 24757526, 2014).
infection (continued). "Moreover, this LDs and FOXO3-mediated immune sensitivity to infection is shown in FOXO3 KO colon with increased bacterial LPS sensing TLR4." (PMID 37298680, 2023). "Interestingly, concomitant Ad-Smad3/Ad-FoxO3 infection significantly reversed cytoplasmic phosphorylated Smad3, largely (p = 0.05) reduced nuclear phosphorylated Smad3, and significantly reduced nuclear total Smad3 compared to Ad-Smad3 infection alone." (PMID 37693008, 2023). "Following establishment of the efficiencies of our Ad-infections and validation of increased transcriptional activities following OE of Smad3 and FoxO3, Western blotting for Smad3 and FoxO3 was performed on Ad-infected whole ASM cell lysates 24 h post-infection." (PMID 37693008, 2023). "In addition, strong nuclear staining for FoxO3 is found in the lungs of patients with a variety of infection-related lung disorders, including cystic fibrosis, chronic obstructive pulmonary disease, and severe pneumonia with acute respiratory distress." (PMID 36233176, 2022). "In addition, upregulated miR-526a positively regulates RIG-I-dependent type I IFN production, and increased miR-155-5p negatively regulated the forkhead box protein O3 (FOXO3)/IRF7 axis to affect type I IFN production during EVA71 infection." (PMID 33809362, 2021). "Moreover, strong nuclear staining of FoxO3 is witnessed in the lungs of patients with various infection-related lung disorders such as cystic fibrosis, chronic obstructive pulmonary disease and severe pneumonia with acute respiratory distress." (PMID 34102081, 2021). "Since the activation of DAF-16 (mammalian homologue Foxo3) in C. elegans can extend lifespan, and resist stress and infection, we hypothesized that gastrodin might mediate neuroprotection by activation of DAF-16." (PMID 31208386, 2019). "Interestingly, while the FOXO3 sense mRNA remains unaltered upon EYFP-ICP4 infection, levels for the EFNB1 mRNA showed a twofold increase." (PMID 29089033, 2017). "The infection status of AM-Cd36 was further supported by the transcriptional alterations observed between virus-positive and virus-negative cells in AM-Cd36, of which genes related to “response to virus” (such as Mx1 and Isg15) and “apoptosis” (such as Bax and Foxo3) were upregulated." (PMID 39414783, 2024). "We observed an initial increase in the FoxO1 and FoxO3 levels between 1 h.p.i. and 12 h.p.i. and a slight decrease later in infection, which could be explained by the increase in miRNAs late in infection." (PMID 36016282, 2022). "After 2 h of infection, the transcriptional upstream regulators EGFR, EGR1, FOXL2, FOXO3, IL1A, IL1B and RELA were activated in MKN-28 cells infected with either H. pylori wt or the ΔhtrA mutant, while WWTR1 was inhibited." (PMID 37193047, 2022). "Infections with adeno‐associated virus (AAV) coding for melusin allowed to investigate whether unloaded muscles preserved contractility, in addition to myofiber CSA, composition in fiber types, myosin heavy chains, levels of atrogene transcripts, and FoxO3 and kinase proteins." (PMID 32154658, 2020). "When analyzing for BIM in direct relation to Bcl-2, we observed that after 6 days of infection, LCMV-specific CD8 T cells from +/+ mice exhibit an increased BIM to Bcl-2 ratio, as compared to FOXO3−/− CD8 T cells." (PMID 22359505, 2012). "We did not observe a change in total FOXO3a expression during infection with ΔmiR-UL36/112/148D, suggesting miR-UL112 alone is insufficient to functionally affect FOXO3 levels during infection." (PMID 39661658, 2024). "In the current study, using GFP fluorescent intensity measurements (for Ad-GFP, Ad-FoxO3, and Ad-Smad3/Ad-FoxO3 cells, all containing IRES elements that precede the GFP coding sequence), we determined Ad-infection efficiencies between 55% and 65% between 24 and 72 h (data not shown)." (PMID 37693008, 2023). "A robust increase in FOXO3 expression without any impact on its phosphorylation level was detected, indicative of the effectiveness of infection." (PMID 33805714, 2021).
infection (continued). "FOXO3 protein expression but not that of FOXO1 was significantly suppressed 3 days after its infection in keratinocytes." (PMID 25647160, 2015). "While we saw no frank signs of uncontrolled infection during the wounding experiments, we observed a decrease in abundance of colonizing bacteria in the healing wound on day 10 in the mice lacking FOXO3 compared to wild-type control." (PMID 24586650, 2014).
cardiovascular diseases (22 papers, 2013 to 2025). "Remarkably, single nucleotide polymorphisms (SNPs) of the FOXO3 gene are associated with longevity and low prevalence of cardiovascular diseases in diverse populations." (PMID 36615135, 2023). "Intriguingly, longevity-associated single nucleotide polymorphisms (SNPs) in human FOXO3 correlate with lower-than-average morbidity from cardiovascular diseases in long-lived people." (PMID 35004893, 2021). "The association of FOXO3 SNPs with self-rated health in individuals aged 75–87 is influenced solely by cardiovascular disease." (PMID 33260156, 2020). "While enhanced FOXO3 activity associated with rs12212067 may be protective in chronic inflammation, e.g., cancer and cardiovascular disease, it appears to be disadvantageous to control acute viral infection." (PMID 36615135, 2023). "To illustrate that not only rare genetics variants, but also rather common genetic polymorphisms may significantly influence the immune response and associated cardiovascular diseases, we briefly discuss here a number of studies on the forkhead transcription factor Foxo3." (PMID 36615135, 2023). "FOXO3 and YWHAB are linked to neurodevelopmental disease, while FOXO3 and ANXA2 are associated with cardiovascular diseases." (PMID 38184718, 2024). "In the case of APOE, APOE ε2 isoform decrease the risk of cardiovascular disease and APOE ε4 isoform limits longevity and FOXO3 is linked to insulin/insulin-like growth factor 1 (IGF1) signaling." (PMID 30926763, 2019). "The findings support further research on FOXO3 and FoxO3 protein as potential targets for therapeutic intervention in aging‐related diseases, particularly cardiovascular disease." (PMID 27071935, 2016). "In addition, Notch1, Smad4, and fork head box O3 (FOXO3) were verified as miR-34a target genes, all of which have actions relevant to cardiovascular diseases." (PMID 35155600, 2021). "Furthermore, the circ-Foxo3 (the circRNA generated from Foxo3) is present in aged patients and murine cardiovascular disease models." (PMID 29723158, 2018).